TRIM21 (tripartite motif containing 21)
Diseases named in the same sentence as TRIM21 in open-access papers (continued):
Sharing a sentence is not in itself a finding about the gene and the disease.
infection (continued). "Upon infection, EV71 upregulates TRIM21 in an IFN-dependent manner; TRIM21 interacts with and degrades SAMHD1 through K48-ubiquitination and proteasomal degradation, thus promoting EV71 replication." (PMID 34552597, 2021). "Despite TRIM21 being IFN-inducible, which is likely crucial to sustain its activity during an ongoing infection, the expression level of TRIM21 is in many cases a limiting factor for the TRIM-Away strategy." (PMID 31555278, 2019). "Infection in the presence of EHRL-4, in contrast, mediated entry of a large number of opsonized ehrlichiae, and these colocalized with TRIM21." (PMID 31548319, 2019). "As we had observed TRIM21‐dependent ASC specking in response to AdV‐h9C12, we investigated the localisation of ASC and intracellular antibody‐coated virus post‐infection." (PMID 31468569, 2019). "The up-regulated TF ZFHX3 targets seven genes in module AD_M25, where two genes OAS1 and RSAD2 are detected in infection pathways, and the other five genes FAM122B, SAMD9, TRIM21, USP18 and IFIT3 are also known to be related to infectious disease." (PMID 30598117, 2018). "Only upon transfection with TRIM21 plasmid, the mRNA expressions of IFN-α/β were significantly up-regulated at both 24 and 48 h post infection." (PMID 30410495, 2018). "First, there are many negative regulators of IFN-I production, and we found that two were increased in expression at days 5 and 15 post-infection (NLRC5 and TRIM21)." (PMID 23737750, 2013). "We found that tripartite motif-containing proteins (TRIMs) including TRIM38, TRIM21, and TRIM14 were significantly enriched during infection with mosquito-borne (West Nile virus strain Kunjin and Zika virus (ZIKV)) and tick-borne (Langat virus (LGTV)) flaviviruses." (PMID 40431659, 2025). "After RABV infection, TRIM21 knockdown reduced the RABV P protein level, genomic RNA level, virus titers, and N protein immunofluorescence of RABV at both 12 and 24 h post infection (hpi)." (PMID 37446070, 2023). "We transfected ubiquitin (Ub) plasmids into mouse primary hepatocytes with or without Ad-TRIM21 infection." (PMID 37249651, 2023). "Furthermore, the expression of several innate immune response regulators (COX-5B, MMP-9, TRIM21, TRIM25 and TRIM26) in the PAMs were also regulated differently during the PRRSV-ADE infection." (PMID 36680075, 2022). "By binding to IgG, IgM and IgA, TRIM21 can target a pathogen regardless of the site of infection and local distribution of antibody isotypes." (PMID 36159815, 2022). "Furthermore, we also found that COX-5B was significantly up-regulated, while TRIM25, TRIM21, TRIM27 and TRIM26 were significantly down-regulated in the PAMs with a PRRSV-ADE infection in this study." (PMID 36680075, 2022). "TRIM21 knockout did not affect cell proliferation or cytopathic MHV‐A59 infection in the absence of serum or antibody." (PMID 34323299, 2021). "Similarly, compared with the uninfected cells, a significantly higher TRIM21 protein level was detected in the HFFs infected with either RH or CEP, at 1–12 h post infection." (PMID 34124071, 2021). "This study is the first to confirm that TRIM21 is constitutively expressed in the cornea of C57BL/6J mice without pathogen infection." (PMID 32373102, 2020). "A recent study demonstrated that TRIM21-mediated intracellular antibody signaling is regulated by the B-Box, which represses TRIM21 ubiquitination and immune activation in the absence of infection." (PMID 31548319, 2019). "Cellular data support a role for phosphorylation, as infection with antibody-bound Ad5 or HRV-14 in cells expressing a S80A TRIM21 mutant did not activate NF-κB, while activation and cytokine production was restored in cells expressing the S80E variant." (PMID 31555278, 2019). "Significant TNFA induction was only observed during infection in the presence of antibody, and not in TRIM21 knockout cells (K21)." (PMID 29667579, 2018).
infection (continued). "It is thus critical that TRIM21 is carefully regulated and only activated during an infection, but it was not clear how this is achieved." (PMID 29667579, 2018). "TRIM21 recruits cellular degradation machinery, including the AAA ATPase VCP and the proteasome, resulting in the destruction of viral particles and neutralization of infection." (PMID 29667579, 2018). "At 15 h post-infection, in vitro vacuoles containing 2 or more parasites were significantly more abundant in cells lacking TRIM21." (PMID 28701773, 2017). "The microbial targets of this arm of intracellular immunity are still being identified: TRIM21 activity has been reported following infection by several non-enveloped viruses and intracellular bacteria." (PMID 31558002, 2016). "During infection with non-enveloped viruses, antibodies stimulate immunity from inside cells by activating the cytosolic Fc receptor TRIM21." (PMID 27881870, 2016). "By facilitating the sensing of incoming rather than progeny genomes, TRIM21 facilitates a rapid immune response upon infection." (PMID 26506431, 2015). "In support of this, we found that TRIM21-dependent signaling is not antagonized by virus-produced HRV protease 3C but is inhibited if the protease is ectopically overexpressed prior to infection." (PMID 26506431, 2015). "In the absence of TRIM21, there was no significant immune induction within the first 8 hours of infection by either AdV or HRV." (PMID 26506431, 2015). "We detected robust transcription of type I interferons, cytokines and ISGs 6 hours post infection in the brain tissue of wild-type but not TRIM21 mice challenged with MAV-1." (PMID 26506431, 2015). "It is of interest that addition of exogenous IFN-α has a substantial effect on neutralization in the context of infection by a replicating virus, which would be expected to activate immune signaling and therefore independently increase IFN-α and TRIM21 production." (PMID 23596308, 2013). "Our work expands our understanding of the antiviral function of TRIM21 against enveloped viruses and suggests that humoral immunity against the CCHFV NP, rather than just a diagnostic marker of infection, may be a key protective host response." (PMID 39455551, 2024). "We therefore evaluated the hypothesis that, after infection, absence of TRIM21 led to diminished T-cell responses against NP and this in turn led to vaccine failure in TRIM21−/− mice." (PMID 39455551, 2024). "On the contrary, kinases IKKβ or TBK1 directly phosphorylate TRIM21 at residue S80 in the LxxIS motif of the RING domain to prevent B-Box inhibition, enhancing E2 binding, RING catalysis, NF-κB activation, and cytokine expression after DNA or RNA viruses’ infection." (PMID 36675197, 2023). "In addition, we sought a better understanding of ubiquitin-mediated PEPCK1 and FASN degradation by transfecting HA-tagged ubiquitin plasmids into mouse primary hepatocytes with or without Ad-TRIM21 infection." (PMID 37249651, 2023). "It is possible that in the context of a prophylactic vaccine or upon repeat infection with a non-persistent pathogen, the Ig-Fc function of TRIM21 may be instrumental in the outcome of host resistance." (PMID 35336995, 2022). "Intriguingly, while Lys-7 ubiquitylation by TRIM21 is critical for p62 oligomerization and protein sequestration, a K13R mutant was still ubiquitylated in HEK293T cells, indicating that modification at Lys-13 may play a unique role during infection." (PMID 31951200, 2020). "As such, complement may synergize with TRIM21 in different ways to prevent cellular infection of non-enveloped viruses." (PMID 31555278, 2019). "A change in TRIM21 phosphorylation upon infection could not be detected but this may be because only a fraction of cellular TRIM21 is recruited and modified during the response." (PMID 29667579, 2018). "Consequently, TRIM21 is activated during infection by diverse pathogens including non-enveloped viruses and intracellular bacteria." (PMID 26506431, 2015).
infection (continued). "Neither STING nor MAVS depletion reduced antibody-dependent signaling 4 hours post infection with either AdV+IgG or HRV+IgG, in agreement with previous results and confirming that the first wave of sensing is primarily dependent on TRIM21 detection of antibody delivery to the cytosol." (PMID 26506431, 2015). "IgM antibodies of the primary repertoire, which TRIM21 can utilize, may be capable of inducing an early response during naïve infection, however we did not observe this during our experiments with MAV-1." (PMID 26506431, 2015). "Using this assay, we show that genetic ablation of TRIM21 or chemical inhibition of either the AAA ATPase p97/valosin-containing protein (VCP) or the proteasome results in a >1,000-fold increase in the relative level of infection in the presence of immune serum." (PMID 23596308, 2013). "More studies are needed to resolve the mechanism, including any role for TRIM21, by which anti-NP CCHFV antibodies protect prior to exposure, but not after infection." (PMID 38409240, 2024). "Infection was not affected in TRIM21 KO cells treated with EHRL-15, demonstrating that this antibody functions independent of TRIM21." (PMID 31548319, 2019). "We also determined the effect of LCMV infection on the expression levels of TRIM21 in infected HEK293T cells and found, that it is not significantly changed upon infection." (PMID 29261807, 2017). "It does not appear that TRIM21 recruited to an antibody‐coated virion acts as a scaffold for inflammasome assembly as, although TRIM21 induced ASC specking in a cell line assay upon infection, there was no co‐localisation of specks with virions in HMDMs." (PMID 31468569, 2019). "Overnight infection with 500× TCID50 MAV-1 did not affect TRIM21 mRNA transcript levels, but pretreatment with IFN-α upregulated TRIM21 gene expression in WT cells, while TRIM21 mRNA remained nondetectable in K21 cells." (PMID 23596308, 2013).
connective tissue diseases (32 papers, 2008 to 2026). "Only one TRIM21-targeted clinical trial has focused on its prognostic value in connective tissue diseases (ClinicalTrials.gov Identifier: NCT03565601)." (PMID 36694250, 2023). "Tests to exclude connective tissue diseases were positive for the anti-Ro-52/TRIM-21 autoantibody." (PMID 31168306, 2019). "Although not disease-specific, anti-Ro52/TRIM21 antibody is a highly frequent and established prognostic biomarker, being an independent risk factor for disease severity and relapse in connective tissue diseases, and of lung involvement in patients with IIMs." (PMID 37835823, 2023).
mouth (5 papers, 2023 to 2025). "In this study, critical factors (including TGR5, carnitine metabolism, and TRIM21) were pinpointed as potential targets for preventing and treating the transition from simple fatty liver to MASH." (PMID 40344326, 2025).
bacterial infections (4 papers, 2012 to 2023). "It should be mentioned that several TRIM genes, whose expression was decreased in the lymph nodes after bacterial infections, were previously reported to take part in T-cell signaling (TRIM21, 27, 28, 32, 33)." (PMID 37686095, 2023). "Whether TRIM21 restricts bacterial infections in vivo remains to be investigated." (PMID 28701773, 2017). "TRIM21, an autoantigen associated with SLE, has been identified as an ubiquitin E3 ligase that targets the transcription factor IRF3 in order to turn off and limit type I IFN production following detection of viral and bacterial infection by Toll Like Receptors (TLRs)." (PMID 22479513, 2012).
infectious disease (4 papers, 2018 to 2024). A disorder directly resulting from the presence and activity of a microbial, viral, or parasitic agent in humans. "TRIM21(Ro52/SS-A) is a target autoantigen that plays a critical role in several systemic autoimmune diseases, infectious diseases, and viral-induced cardiac injuries." (PMID 36439111, 2022). "Variations in how TRIM21 regulates distinct molecules during inflammation result in it displaying contrasting immune responses, either anti-inflammatory or pro-inflammatory, across various infectious diseases." (PMID 39165359, 2024).
cardiovascular diseases (3 papers, 2019 to 2025). "Following a literature review, we chose four RBPs (HSPA1A, ZFP36, TRIM21, and P2RX7) that play important roles in the development of cardiovascular diseases for further co-expression analysis." (PMID 37180137, 2023).
gastrointestinal tumors (3 papers, 2023 to 2025). "Together, these results indicated that high expression of TRIM21 in multiple GI tumors was associated with poor patient prognosis and that the TRIM21 expression level was elevated further in response to ferroptosis inducer treatment." (PMID 37587773, 2023). "Additionally, we determined that TRIM21 was highly expressed in multiple GI tumors and was further upregulated upon ferroptosis induction." (PMID 37587773, 2023).
metabolic disorder (2 papers, 2023 to 2026). "This leads us to speculate that TRIM21 may play a crucial role in alleviating hepatic cell carcinoma development caused by metabolic disorders." (PMID 37249651, 2023). "To investigate whether TRIM21 expression is associated with human metabolic disorders, we first utilized bioinformatic analysis to observe the TRIM21 expression in type 2 diabetic patients." (PMID 37249651, 2023). "Moreover, it is worthwhile to elucidate the mechanism of how TRIM21 expression was regulated in the liver with metabolic disorders in the future." (PMID 37249651, 2023).
neurological disorders (2 papers, 2016 to 2022). "For other diagnoses (in the absence of a known organ-specific or systemic immunological disorder), there were higher proportions of patients with isolated anti-Ro52/TRIM21 who had malignancies, neurological disorders and respiratory diseases." (PMID 35871174, 2022).
adenocarcinoma (1 paper, 2023). A common cancer characterized by the presence of malignant glandular cells. "The analysis showed that high levels of TRIM21 were significantly associated with better OS in adenocarcinoma, suggesting that detecting TRIM21 expression levels in patients with adenocarcinoma may help to predict their prognosis." (PMID 37335642, 2023).
TRIM21 also shares sentences with these, for which no sentence is quoted: Arthritis (15 papers); neonatal lupus (14); polymyositis (13); idiopathic inflammatory myopathies (12); congenital heart block (11); diffuse large B-cell lymphoma (10); mixed connective tissue disease (10); antisynthetase syndrome (9); autoimmune liver diseases (8); inflammatory myopathy (8); xerostomia (8); leukopenia (7); primary biliary cholangitis (7); dry eye (6); alopecia (4); atrioventricular block (4); Cirrhosis (4); disseminated candidiasis (4); pulmonary arterial hypertension (4); brain tumor (3); celiac disease (3); cutaneous vasculitis (3); dermatitis (3); heart diseases (3); immune disease (3); juvenile myositis (3); lupus nephritis (3); nephritis (3); renal disease (3); sarcoidosis (3).
A further 149 diseases each share a sentence with TRIM21 in 3 papers or fewer.